LAMA3 (laminin subunit alpha 3)
Diseases named in the same sentence as LAMA3 in open-access papers (continued):
Sharing a sentence is not in itself a finding about the gene and the disease.
laryngo-onycho-cutaneous syndrome (5 papers, 2021 to 2024). LOC syndrome is a subtype of junctional epidermolysis bullosa (JEB) characterized by an altered cry in the neonatal period and by aberrant production of granulation tissue in particular affecting the upper airway tract, conjunctiva and periungual/subungual sites. "Shabbir Syndrome or commonly known as Laryngo-onycho-cutaneous syndrome (LOCS) is an autosomal recessively inherited syndrome, caused due to mutations in the laminin alpha-3 (LAMA3) gene." (PMID 38328664, 2024). "Therefore, Pakistani Punjabi families affected with Shabbir Syndrome may be screened for c.151dup variant in LAMA3 using targeted sequencing." (PMID 37492301, 2023). "LOC syndrome is classified as a rare subtype of JEB, mainly caused by the same founder mutation (c.151insG) in exon 39 of the LAMA3 gene." (PMID 33921969, 2021). "A special phenotype, laryngo-onycho-cutaneous syndrome(LOC syndrome), manifests pathogenic variants that forma stop codon in exon 39, specific for the alpha-3 subunit ofthe LAMA3 gene, where three causative variants have beendescribed so far: p.V51fs; p.Gln157Ter; p.Trp16Ter (Wanget al., 2022)." (PMID 36923479, 2023).
lung fibrosis (4 papers, 2019 to 2025). "While lung‐specific loss of LAMA3 aggravated BLM‐induced pulmonary fibrosis, our attention was drawn to NPNT due to its high enrichment in the lungs compared to other organs." (PMID 40444575, 2025). "In addition, laminin subunit alpha 3, detected at + 14.17 fold and + 13.78 fold at 72 and 96 h, respectively, is increased in pulmonary fibrosis." (PMID 40665229, 2025). "Utilizing these identified genes, integrated proteomic analysis of IPF patients and bleomycin (BLM)‐induced pulmonary fibrosis in mice, we discovered that NPNT and lamininα3 (LAMA3) were the only genes consistently downregulated at both mRNA and protein levels in fibrotic lung tissues." (PMID 40444575, 2025). "Several of these genes (PELI1, MAP3K8, LAMA3, EMP2, CTNNAL1, CAV1, LRRK2, SFRP4) may also be involved in lung fibrosis, a severe complication of COVID-19." (PMID 37561814, 2023).
adenoma (3 papers, 2013 to 2025). A neoplasm arising from the epithelium. "We found that CDH20 and LAMA3 were mutated in the adenoma while NRXN3 and COL4A6 were mutated in the adenocarcinoma." (PMID 23301059, 2013). "Time series analysis using the likelihood ratios showed differences in expression of genes including Fos, Lama3, Aldh1a3, Col7a1 and Doks associated with increased induction by t = 12 h, whereas E2f8, Exo1, Clspn, Kif14 and Kif12 all were decreased in Smad4+/+ adenomas." (PMID 40348815, 2025). "First, a missense mutation in LAMA3 in adenoma changed from leucine to serine." (PMID 23301059, 2013). "CDH20 and LAMA3 were mutated in the adenoma while NRXN3 and COL4A6 were mutated in the adenocarcinoma from the same patient, suggesting for the first time that genetic alterations in the cell adhesion pathway occur as early as in the adenoma." (PMID 23301059, 2013).
enamel hypoplasia (3 papers, 2020 to 2025). "Interestingly, in a family of a patient with Intermediate JEB due to a mutation in LAMA3, where the affected individual presented with occasional oral erosions and enamel hypoplasia, two healthy carriers of the LAMA3 null mutations also had enamel defects, consisting of roughness and pits." (PMID 33202040, 2020). "Individuals with EB caused by mutations in laminin-332 (Lama3, Lamb3, Lamc2), α6ß4-integrin (TGB4, ITGA6) gene and type XVII collagen (Col17A1) are associated with enamel hypoplasia." (PMID 37511997, 2023).
lung carcinoma (3 papers, 2015 to 2021). "LAMA3 abnormal methylation is involved in the occurrence, development and prognosis of various malignant tumors such as pancreatic cancer, gastric cancer, head and neck tumors, and lung cancer." (PMID 33992120, 2021).
pancreatic adenocarcinoma (3 papers, 2021 to 2024). "Other researchers found that a combined signature of high LAMA3, LAMB3, and LAMC2 expression was a stronger predictor of poor prognosis in pancreatic adenocarcinoma than individual genes." (PMID 39218967, 2024). "We used Gene Expression Omnibus (GEO) database and identified six genes (COL1A2, ITGA2, ITGB6, LAMA3, LAMB3, and LAMC2) that could affect the survival rate of pancreatic adenocarcinoma patients." (PMID 35899199, 2022).
amelogenesis imperfecta (2 papers, 2021 to 2022). Amelogenesis imperfecta (AI) represents a group of developmental conditions affecting the structure and clinical appearance of the enamel of all or nearly all the teeth in a more or less equal manner, and which may be associated with morphologic or biochemical changes elsewhere in the body. "Mutations in AMELX, DLX3, LAMA3, LAMB3, and WDR72 were reported in both non-syndromic and syndromic amelogenesis imperfecta." (PMID 33672174, 2021).
autoimmune disease (2 papers, 2023). A disorder resulting from loss of function or tissue destruction of an organ or multiple organs, arising from humoral or cellular immune responses of the individual to their own tissue constituents. "Gene set analysis of the 100 most significant genes in the DNAemia meta-analysis found significant enrichment of genes associated with autoimmune disease of skin and connective tissue (DOID:0060039: FDR = 0.02; TG, DSG1,DST, LAMA3, HLA-DRB1)." (PMID 38005904, 2023).
breast tumors (2 papers, 2018 to 2023).
cholangiocarcinoma (2 papers, 2023 to 2024). A carcinoma that arises from the intrahepatic biliary tree (intrahepatic cholangiocarcinoma) or from the junction, or adjacent to the junction, of the right and left hepatic ducts (hilar cholangiocarcinoma). "The upregulation of LAMA3 influenced the growth, attachment, movement, and transition from epithelial to mesenchymal states in cholangiocarcinoma cells." (PMID 38893622, 2024).
and neck cancer (1 paper, 2024). "and neck cancer (HNC), the invasion-associated molecules LAMA3, LAMC2, THBS1, IGF1R, PDGFB, and transforming growth factor β1 can serve as prognostic indicators or molecular therapeutic targets to improve the survival rates of HNC." (PMID 38877482, 2024).
androgenetic alopecia (1 paper, 2023). "The results showed that Lama3 mutant mice started to show signs of androgenetic alopecia on the 80th day after birth." (PMID 38012251, 2023). "This study is a good extension of the current body of knowledge about the function of the Lama3 gene, and the constructed Lama3 single-base mutant mouse may be an animal model for the study of androgenetic alopecia." (PMID 38012251, 2023). "This study is a good extension of the current body of knowledge about the function of Lama3, and the constructed Lama3 (R217C) mutant mice may be a good animal model for studying androgenetic alopecia." (PMID 38012251, 2023).
anemia (1 paper, 2021). A reduction in the number of red blood cells, the amount of hemoglobin, and/or the volume of packed red blood cells. "LAMA3 has been previously associated with reticulocyte count, a blood biomarker for hematologic abnormalities, like anemia, which is one of the most frequent extra-articular organ manifestations in RA." (PMID 34260700, 2021).
aneurysm (1 paper, 2009). Bulging or ballooning in an area of an artery secondary to arterial wall weakening. "Perhaps more important to the predilection of the suprarenal aorta to aneurysm formation are the downregulation of a number of genes coding for structural extracellular matrix proteins including Lama3, Myo18b and the cytoskeletal protein Tuba8." (PMID 19580648, 2009).
asthma (1 paper, 2020). "These genes included RBM42, STX5, and TRIM41 in asthma, CYP27A1, GM2A, LGALS9, SPI1, and NLRC4 in COPD, ATF3, PPP1R15A, ZFP36, SOCS3, NAMPT, and GADD45B in IPF, LRRC48 and CETN2 in asthma-COPD, COL15A1, GIMAP6, and JAM2 in asthma-IPF and LMO7, TSPAN13, LAMA3, and ANXA3 in COPD-IPF." (PMID 31952466, 2020). "In addition, other identified genes were LRRC48 and CETN2 in asthma-COPD, COL15A1, GIMAP6, and JAM2 in asthma-IPF, along with LMO7, TSPAN13, LAMA3, and ANXA3 in COPD-IPF." (PMID 31952466, 2020).
bone tumors (1 paper, 2012). "High-level amplification of TGFβ2 (1q41), CCND3 (6p21), WI-6509 (11qtel), SHGC-5557 (12ptel), TCL1A (14q32.1), CREBBP (16q13.3), HIC1 (17p13.3), THRA (17q11.2), AFM217YD10 (17qtel), LAMA3 (18q11.2), RUNX1 (21q22.3) and D22S543 (22q11), was commonly observed in aggressive bone tumors." (PMID 23199169, 2012).
chronic pancreatitis (1 paper, 2023). A chronic inflammatory process causing damage and fibrosis of the pancreatic parenchyma. "Other observations included a less robust correlation between LAMA3 with pathological stages (p = 0.04) and LAMB3 with male patients (p = 0.02) and with chronic pancreatitis history (p = 0.03)." (PMID 37779898, 2023).
colon cancer (1 paper, 2022). "These genes encode the extracellular matrix proteins LAMA3 and LAMC2, which have been detected in invasive colon cancer cells and are regulated by transforming growth factor beta 1 and the hepatocyte growth factor produced in the tumor microenvironment." (PMID 36077674, 2022).
colorectal adenoma (1 paper, 2013). An adenoma that arises from the colon or rectum. "First, CDH20 and LAMA3, which are both involved in cell adhesion, were found to be mutated in the colorectal adenoma." (PMID 23301059, 2013).
Crohn disease (1 paper, 2024). A gastrointestinal disorder characterized by chronic inflammation involving all layers of the intestinal wall, noncaseating granulomas affecting the intestinal wall and regional lymph nodes, and transmural fibrosis. "Lama3 has also been shown to be expressed in Crohn’s disease." (PMID 38646621, 2024).
enteritis (1 paper, 2024). Inflammation of the small intestine. "In our study, the expression of Lama3 was visibly elevated after the addition of C. butyricum, and C. butyricum B14 promoted the healing of damaged parts of enteritis." (PMID 38646621, 2024).
fibrosis (1 paper, 2025). the formation of excess fibrous connective tissue in an organ or tissue in a reparative or reactive process. "Five variable multi-omics analysis provided more granular understanding of the core differences in expression between groups, with ELOVL2, LIPK, LAMA3, and lncRNAs partnered with UHRF1BP1L and S1PR1 found to most reliably discriminate the control and fibrosis groups." (PMID 40040391, 2025).
gastric cancer (1 paper, 2019). A primary or metastatic malignant neoplasm involving the stomach. "In addition, a study on gastric cancer has suggested LAMB3 and LAMC2 chains accumulate intracellularly and are related with cancer progression, while epigenetic silencing of the LAMA3 chain may lead to an inability of synthesizing the basement membrane, which may affect cancer cell invasion." (PMID 31182680, 2019).
human papillomavirus infection (1 paper, 2021). "KEGG pathway enrichment of LAMA3 interactive genes showed that ECM-receptor interaction, focal adhesion, PI3K-Akt signaling pathway, human papillomavirus infection were the most enriched pathways." (PMID 33992120, 2021). "Our KEGG pathway and GO biological processes results indicate that LAMA3 may participate in ECM-receptor interaction, focal adhesion, PI3K-Akt signaling pathway, human papillomavirus infection, cell adhesion, cell differentiation, cell migration." (PMID 33992120, 2021).
Hypodontia (1 paper, 2023). The absence of five or less teeth from the normal series by a failure to develop. "The exact mechanism by which LAMA3 mutations lead to hypodontia is not fully understood, but it is thought to be related to the role of laminin-5 in tooth bud development and the attachment of teeth to the surrounding tissues." (PMID 37745851, 2023). "LAMA3 mutations have also been previously reported in non-syndromic hypodontia patients." (PMID 37745851, 2023).
Infertility (1 paper, 2019). "LAMA3 has been identified in the uterus of several species during implantation, and decreased expression may be associated with reduced uterine receptivity and infertility." (PMID 31035421, 2019).
invasive ductal carcinoma (1 paper, 2020). "For validation, the feature and spatial feature plots of MAF, CD248, GJA1, LAMA3, TJP1, LAMC2, and COL17A1 demonstrated to show the location in BRCA samples, and they were highly-expressed in the invasive ductal carcinoma tissue (cluster 2, 4, 7, 9, 12)." (PMID 33585235, 2020).
metastasis (1 paper, 2024). The spread or migration of cancer cells from one part of the body (where they first appeared) to another. "Univariate analysis revealed that histological grade, TNM stage, vascular invasion, and high LAMA3 expression were significantly associated with liver metastasis." (PMID 38452390, 2024).
metastatic tumor (1 paper, 2012). "In our data, the most remarkable change in metastatic tumor was occurred at increases (≧1.30) of D1S1635 (1p36.22), D1S214 (1p36.31), EXT1 (8q24.11-q24), AFM137XA11 (9p11.2), CCND2 (12p13), 8 M16/SP6 (12ptel), IGH (D14S308), HIC1 (17p13.3), 282 M15/SP16 (17ptel), and LAMA3 (18q11.2)." (PMID 23199169, 2012).
myocardial infarction (1 paper, 2024). Gross necrosis of the myocardium, as a result of interruption of the blood supply to the area, as in coronary thrombosis. "LAMA1, LAMA3 and LAMA5, other laminins, are targets of the approved drug lanoteplase, used in the treatment of myocardial infarction but with unknown mechanisms of action." (PMID 38383672, 2024).
Oligodontia (1 paper, 2022). The absence of six or more teeth from the normal series by a failure to develop. "The heterozygous nonsense variant of the LAMA3 gene identified in a patient with oligodontia (p.Glu306Ter, rs771405735) was reported in a ClinVar as a variant of uncertain significance for the autosomal recessive junctional epidermolysis bullosa gravis of Herlitz." (PMID 36294409, 2022).
oral cancer (1 paper, 2024). "The upregulated expression levels of LAMA3 in oral cancer tissues were substantiated through qRT-PCR and immunohistochemical staining." (PMID 38877482, 2024). "OSCC and paracancerous tissues from patients (n = 10) were randomly selected for qRT-PCR, and the level of LAMA3 mRNA in oral cancer tissues was significantly higher than that in paracancerous tissues (P < 0.05)." (PMID 38877482, 2024). "To confirm the expression levels of the BMG LAMA3 in clinical samples of oral cancer tissue, we performed quantitative real-time PCR (qRT-PCR) and immunohistochemical staining." (PMID 38877482, 2024). "Whatmore, one-way Cox regression analysis showed that three BMGs, LAMA3, MMP14, and GPC2, were significant prognostic predictors in oral cancer patients." (PMID 38877482, 2024).
osteoporosis (1 paper, 2022). A condition of reduced bone mass, with decreased cortical thickness and a decrease in the number and size of the trabeculae of cancellous bone (but normal chemical composition), resulting in increased fracture incidence. "In detail, osteoporosis was found in 3 patients, 2 patients affected by JEB with LAMA3 deficit and 1 patient with TKS." (PMID 35379269, 2022).
prion disease (1 paper, 2014). A transmissible disease that is caused by a protein that is able to induce abnormal folding of normal cellular proteins, leading to characteristic spongiform brain changes, which are associated with neuronal loss without an inflammatory response. "Four proteins (NRXN2, KLKB1, KARS, and LAMA3) that harbour rarely observed single-nucleotide variants showed biological interactions that are associated with prion diseases and/or prion protein in our biological network analysis." (PMID 25149502, 2014). "Four proteins (NRXN2, KLKB1, KARS, and LAMA3) that harbour rarely observed SNVs have biological interactions that are associated with prion diseases and/or prion protein." (PMID 25149502, 2014).
respiratory failure (1 paper, 2022). The significant impairment of gas exchange within the lungs resulting in hypoxia, hypercarbia, or both, to the extent that organ tissue perfusion is severely compromised. "PT25 with LAMA3 mutations and PT24 with ITGB4 mutations expired within a few months after birth from sepsis and respiratory failure." (PMID 36578049, 2022).
serous ovarian cancer (1 paper, 2021). "As a new biomarker of chemotherapy sensitivity, hypermethylation of NCALD and LAMA3 is associated with poor PFS in advanced high-grade serous ovarian cancer." (PMID 34289901, 2021). "We identified 3 new methylation genes (ITGB6, NCALD and LAMA3) with different chemotherapy outcomes in advanced high-grade serous ovarian cancer." (PMID 34289901, 2021). "For the first time, the role of DNA methylation in regulating the function of NCALD and LAMA3 genes in advanced high-grade serous ovarian cancer was pointed out." (PMID 34289901, 2021). "In advanced high-grade serous ovarian cancer, NCALD and LAMA3 have hypermethylation and low expression in chemoresistant patients." (PMID 34289901, 2021). "In advanced high-grade serous ovarian cancer, 8 CpGs (ITGB6:cg21105318, cg07896068, cg18437633; NCALD: cg27637873, cg26782361, cg16265707; LAMA3: cg20937934, cg13270625) remained hypermethylated in chemoresistant patients." (PMID 34289901, 2021). "In advanced high-grade serous ovarian cancer, ITGB6, NCALD and LAMA3 hypermethylation indicate chemotherapy resistance and poor prognosis." (PMID 34289901, 2021). "In the tissue array composed of 132 advanced high-grade serous ovarian cancer patient samples, immunohistochemistry also showed that the expression of NCALD and LAMA3 in chemoresistant patients was lower than that of chemosensitive patients (57.89% VS 39.58%, P = 0.048; 54.67% VS 42.55%, P = 0.041)." (PMID 34289901, 2021).